BAIAP2L1 (BAR/IMD domain containing adaptor protein 2 like 1)
Description:
May function as adapter protein. Involved in the formation of clusters of actin bundles. Plays a role in the reorganization of the actin cytoskeleton in response to bacterial infection.
Synonyms: IRTKS
Tractability: Antibody: its Gene Ontology location is reachable by antibodies, with high confidence; the Human Protein Atlas places it where antibodies can reach. PROTAC: ubiquitination databases record sites on it; its protein half-life has been measured.
Gene: Protein-coding gene on chromosome 7 (98,291,648 to 98,401,115, reverse strand). Ensembl gene ENSG00000006453.
Subcellular location: Cytoplasm, cytoskeleton
Subcellular location (Human Protein Atlas): Plasma membrane; Cytosol
Pathways (Reactome):
Signal Transduction: RAC1 GTPase cycle; RAC2 GTPase cycle; RAC3 GTPase cycle; RHOF GTPase cycle
Gene Ontology:
Molecular function: cadherin binding involved in cell-cell adhesion; proline-rich region binding; protein binding
Biological process: positive regulation of actin filament polymerization; regulation of actin cytoskeleton organization; actin crosslink formation; actin filament bundle assembly; cell-cell adhesion; plasma membrane organization; regulation of actin filament polymerization
Cellular component: actin cytoskeleton; adherens junction; cytosol; extracellular exosome; plasma membrane; cytoskeleton
Genetic constraint (gnomAD): Loss-of-function variants: 29 observed, 59.07 expected, observed/expected ratio (o/e) 0.49, 90% interval 0.37 to 0.67. The upper end of that interval is the gene's LOEUF score, 0.67, which puts it in group 2 of 6, group 1 being the genes least tolerant of losing a copy. Missense variants: 569 observed, 593.72 expected, observed/expected ratio (o/e) 0.96, 90% interval 0.89 to 1.03. Synonymous variants: 242 observed, 219.38 expected, observed/expected ratio (o/e) 1.1, 90% interval 0.99 to 1.23.
Homologues: Orthologues: chimpanzee BAIAP2L1 (99% identical), macaque BAIAP2L1 (96% identical), chimpanzee BAIAP2L1 (95% identical), mouse Baiap2l1 (88% identical), rat Baiap2l1 (88% identical), guinea pig BAIAP2L1 (86% identical), dog BAIAP2L1 (84% identical), rabbit BAIAP2L1 (83% identical), pig BAIAP2L1 (82% identical), tropical clawed frog baiap2l1 (62% identical), zebrafish baiap2l1b (55% identical), zebrafish baiap2l1a (51% identical), and 1 more. Paralogues in human: BAIAP2 (40% identical), BAIAP2L2 (30% identical).
Diseases named in the same sentence as BAIAP2L1 in open-access papers:
BAIAP2L1 is named in the same sentence as 34 diseases in open-access papers, as found by Europe PMC text mining. Sharing a sentence is not in itself a finding about the gene and the disease. The quoted sentences say what the papers report.
lung carcinoma (4 papers, 2015 to 2021). "Three genes, P4HA2, TJP3, and BAIAP2L1, have been shown to be associated with lung cancer B lymphocytes in situ." (PMID 34575089, 2021). "BAIAP2L1(BAI1-associated protein 2-like 1) was reported as another fusion partner of FGFR3 in lung cancer patients and BC cell lines." (PMID 27930669, 2016). "Another gene, BAIAP2L1, is a general regulator associated with the tumor microenvironment, which may identify lung cancer B lymphocytes." (PMID 34575089, 2021). "Up-regulation of BAIAP2L1 was observed in clear cell Renal Carcinoma (confirmed also by our data on a surgically removed ccRCC), in lung cancer and recently even in prostate cancer." (PMID 34209090, 2021). "Oncogenic FGF receptor 3 (FGFR3)-BAIAP2L1 fusion gene was identified in bladder cancers and lung cancers, and its identification may aid in selecting patients for FGFR-targeted therapy." (PMID 26222696, 2015). "Although oncogenic FGF receptor 3 (FGFR3)-BAIAP2L1 fusion gene has been identified in bladder cancers and lung cancers, we could not detect the transcript of fusion genes of BAIAP2L1 in this study of a limited number of specimens." (PMID 26222696, 2015).
ovarian carcinoma (4 papers, 2015 to 2025). A malignant neoplasm originating from the surface ovarian epithelium. "Interestingly, positive genetic correlations are observed between UF and ovarian cancer, and it can be assumed that one of the genes that may underlie these correlations may be the BAIAP2L1 gene." (PMID 40724651, 2025). "Functional assays in ovarian cancer cells revealed that BAIAP2L1 is involved in promoting cell proliferation and avoiding apoptosis." (PMID 26222696, 2015). "Protein levels of BAIAP2L1 in 193 ovarian cancer tissues, containing serous, endometrioid, clear cell, and mucinous cell types were analyzed." (PMID 26222696, 2015). "Knockdown of BAIAP2L1 with siRNA technology inhibited cell growth in multiple ovarian cancer cell lines, shown in results of BrDU incorporation assays and MTT assays." (PMID 26222696, 2015). "In agreement with RNA expression results, BAIAP2L1 protein expression is higher in ovarian cancer than in normal tissues, as shown in FDA805-1and 805–2 tissue arrays." (PMID 26222696, 2015). "Results of this study not only indicate that BAIAP2L1 can be used as a biomarker for human ovarian cancer but also reveal its role in cancer biology." (PMID 26222696, 2015). "Upregulation of BAIAP2L1 in ovarian tumors was first found during RNA screening and confirmed by immunohistochemical studies on ovarian cancers and other cancer types." (PMID 26222696, 2015). "In conclusion, results of this study not only indicate that BAIAP2L1 can be used as a biomarker for human ovarian cancer but also reveal its role in cancer biology." (PMID 26222696, 2015). "Since BAIAP2L1 has been shown to promote cell proliferation in hepatocellular carcinoma (HCC), we also tested the role of BAIAP2L1 in cell growth of ovarian cancer cells." (PMID 26222696, 2015). "Significant upregulation of BAIAP2L1 in ovarian cancer was validated by analyzing multiple independent cohorts in publicly available data sets." (PMID 26222696, 2015). "Functional assays in ovarian cancer cells indicate that BAIAP2L1 is involved in promoting cell proliferation and avoiding apoptosis." (PMID 26222696, 2015). "GSE2109 data set further revealed that BAIAP2L1 was significantly higher in 49 ovarian cancer cell lines (9.4 ± 0.17) than 972 cancer cell lines derived from other tissues (8.6 ± 0.07) (p = 0.004)." (PMID 26222696, 2015). "Data in GSE14407 data set indicated that BAIAP2L1 mRNA expression was significantly higher in ovarian cancer epithelial cells (CEPI, 11.8 ± 0.28 shown as mean ± standard error) than in normal ovarian surface epithelia (OSE, 10.8 ± 0.22) (p = 0.004)." (PMID 26222696, 2015). "Expression of BAIAP2L1 was further analyzed in 14 paired samples of primary ovarian cancers and their corresponding metastatic sites." (PMID 26222696, 2015). "Public domain datasets were used to validate that the expression of BAIAP2L1 is significantly higher in ovarian cancer than normal tissues and other types of cancer." (PMID 26222696, 2015). "In this study, we report the first comprehensive study of BAIAP2L1 upregulation in human ovarian cancer." (PMID 26222696, 2015). "These include CTSB in OAC, BAIAP2L1 in ovarian cancer and BCAR1 in a range of cancers." (PMID 28859074, 2017). "Similarly, mRNA expression of BAIAP2L1 in ovarian cancer cell lines was higher than normal cell lines." (PMID 26222696, 2015). "Our findings that BAIAP2L1 histoscores of metastatic sites are higher than primary ovarian cancers suggest that BAIAP2L1 may contribute to tumor invasion and metastasis." (PMID 26222696, 2015). "We report here the first comprehensive study of BAIAP2L1 upregulation in ovarian cancers." (PMID 26222696, 2015). "The BAIAP2L1 gene may serve as a biomarker in ovarian cancer." (PMID 36362120, 2022). "In this study, integrative database analyses of BAIAP2L1 in GSE14407 and GSE36133 cancer tissues as well as GSE2109 cell lines validate our immunohistochemical results of high BAIAP2L1 expression in ovarian cancers." (PMID 26222696, 2015).
ovarian carcinoma (continued). "Expression levels of BAIAP2L1 were not different among various cell types of ovarian cancer, stage and grade of each histologic subtype, but each type of ovarian cancer expressed significantly higher BAIAP2L1 than normal ovarian tissues." (PMID 26222696, 2015). "To date, the role of BAIAP2L1 in ovarian cancer has not been defined." (PMID 26222696, 2015). "None of 8 tested ovarian cancer RNA contained the transcript of fusion gene between FGFR and BAIAP2L1, while the RNA of bladder cancer SW780 cells expressed transcripts of the fusion gene." (PMID 26222696, 2015).
Obesity (3 papers, 2012 to 2025). Accumulation of substantial excess body fat. "BAIAP2L1 is also known as IRTKS (insulin receptor tyrosine kinase substrate) which is involved in insulin receptor signaling and may relate to insulin resistant states including obesity and T2D." (PMID 22829776, 2012).
clear cell renal cell carcinoma (2 papers, 2020 to 2021). "In clear cell renal cell carcinoma (ccRCC), CLIP4 mutations are three-fold higher in patients with aggressive tumors than in those without aggressive ccRCC, and high expression levels of MOCOS, BAIAP2L1, DDX11, and CLIP4 are markedly associated with poor OS." (PMID 33575272, 2020).
diabetes (2 papers, 2015). "Furthermore, hepatic expression of BAIAP2L1 was decreased in mice and humans with type 2 diabetes, suggesting an association between BAIAP2L1 downregulation and the development of diabetes." (PMID 26222696, 2015).
hepatocellular carcinoma (2 papers, 2015 to 2019). A malignant tumor that arises from hepatocytes. "BAIAP2L1 is recently reported to promote cell proliferation through activation of the EGFR-ERK pathway in hepatocellular carcinoma." (PMID 26222696, 2015). "In tumorigenesis, BAIAP2L1 has been reported to promote cell proliferation through activation of the EGFR-ERK pathway in hepatocellular carcinoma." (PMID 26222696, 2015). "BAIAP2L1 expression has been shown to increase in hepatocellular carcinoma." (PMID 26222696, 2015).
lymphoma (2 papers, 2017 to 2020). A malignant (clonal) proliferation of B- lymphocytes or T- lymphocytes which involves the lymph nodes, bone marrow and/or extranodal sites. "This small in-frame deletion likely does not have a significant effect on protein function, however, there is strong evidence that BAIAP2L1 promotes cell proliferation and inhibits apoptosis and BAIAP2L2 may have a similar role in dog and human lymphoma." (PMID 32857815, 2020).
melanoma (2 papers, 2022 to 2024). A malignant, usually aggressive tumor composed of atypical, neoplastic melanocytes. "As a result of this screen, we showed that the I-BAR protein BAIAP2L1 (IRTKS) is an FMNL2-binding protein required for FMNL2-induced filopodia assembly in melanoma cells." (PMID 38891874, 2024).
Arthritis (1 paper, 2012). Inflammation of a joint. "BAIAP2L1 (7q21.3) encodes a protein important in cytoskeleton organization that has been associated with the inflammatory marker CRP in patients with arthritis." (PMID 22829776, 2012).
asthma (1 paper, 2025). "Taken together, this data indicates that BAIAP2L1, a gene that was downregulated in IgM-deficient mice has a stimulant-specific role in inducing airway contraction of bronchial smooth muscle cells during asthma." (PMID 41401081, 2025).
endometriosis (1 paper, 2025). The growth of functional endometrial tissue in anatomic sites outside the uterine body. "At the same time, two genetic markers—rs440837 (A > G) ZBTB10 (it is an independent risk factor for endometriosis) and rs3779195 (T > A) BAIAP2L1, have been involved in the formation of the largest number of SNP-SNPinter models—4 and 3 models, respectively." (PMID 41373783, 2025). "Endometriosis-associated SNP-SNPinter models include 7 SNPs from 9 analyzed loci, such as rs17496332 (A > G) PRMT6, rs780093 (C > T) GCKR, rs10454142 (T > C) PPP1R21, rs3779195 (T > A) BAIAP2L1, rs440837 (A > G) ZBTB10, rs7910927 (G > T) JMJD1C, and rs8023580 (T > C) NR2F2." (PMID 41373783, 2025).
ovarian tumors (1 paper, 2015). "Upregulation of BAIAP2L1 in ovarian tumors was first revealed on Clontech Cancer Profiling Array and confirmed with immunohistochemical studies." (PMID 26222696, 2015).
rheumatoid arthritis (1 paper, 2015). A chronic, systemic autoimmune disorder characterized by inflammation in the synovial membranes and articular surfaces. "BAIAP2L1 has also been shown in the disease progression of rheumatoid arthritis, where BAIAP2L1 expression in fibroblast-like synovial cells was positively correlated with C-reactive protein (CRP), a common clinical marker for inflammation." (PMID 26222696, 2015).
tumor (13 papers, 2014 to 2026). "In all three tissue types, BAIAP2L1 expression levels in tumor tissues were significantly higher than normal tissues." (PMID 26222696, 2015). "While global methylation changes do not consistently predict transcriptional output, locus-specific effects, notably in DSCAML1, BAIAP2L1, and SHANK1, suggest potential mechanistic relevance and potential functional impact on tumor biology." (PMID 41597272, 2026). "Frozen tumor tissues and plasma were used to measure PBRM1, BAP1, SET domain-containing 2 (SETD2), KDM5C, FOXC2, CLIP4, AQP1, DDX11, BAIAP2L1, and TMEM38B mRNA levels, and correlation with the Fuhrman grade was investigated." (PMID 32392781, 2020). "A prospective study examining frozen tissue qRT-PCR of AQP1, DDX11, BAIAP2L1, and six previously identified genes (PBRM1, BAP1, SETD2, KDM5C, FOXC2, and CLIP4) showed that expression of DDX11 was a significant factor for predicting tumor aggressiveness based on Fuhrman grade." (PMID 31963294, 2020).
cancer (10 papers, 2015 to 2026). A tumor composed of atypical neoplastic, often pleomorphic cells that invade other tissues. "Malignant tumors exhibited global hypomethylation compared to benign tumors, except for specific loci such as cg08684580 in BAIAP2L1, which showed higher methylation levels in malignant samples." (PMID 41597272, 2026). "The inverse BAIAP2L1 methylation–expression relationship suggests potential regulatory silencing of BAIAP2L1, consistent with the broader role in cancer cell migration and metastasis." (PMID 41597272, 2026). "Further elucidation of the role of BAIAP2L1 in context of the insulin receptor signaling pathways of cancer cells is warranted for developing cancer therapeutics by targeting cancer-specific metabolism." (PMID 26222696, 2015). "Further elucidation of the role of BAIAP2L1 in context of the IR-IRS-downstream effectors pathways of cancer cells is warranted for developing cancer therapeutics targeting cancer-specific metabolism." (PMID 26222696, 2015). "In the tissue expression level, GSE36133 data set showed that BAIAP2L1 was significantly higher in 182 primary ovarian and fallopian tubal cancers (10.4 ± 0.09) compared to 1680 primary cancers mostly from breast, colon, rectum, endometrium, lung, and kidney (9.8 ± 0.04) (p = 4.5 x 10−7)." (PMID 26222696, 2015). "Future studies may prove that BAIAP2L1 is involved in getting more glucose entry to cancer cells, perhaps by increasing the efficiency of Glut transporters." (PMID 26222696, 2015). "Benign versus malignant comparisons identified 101 differentially methylated CpGs, including hypermethylated CpG in BAIAP2L1 and hypomethylated CpG in SHANK1 in malignant tumors." (PMID 41597272, 2026). "BAIAP2L1, the GMR of nodule “C” was up-regulated in all three cancer regions (by 1.76× in “A”, 2.54× in “B”, and 1.92× in “C”)." (PMID 34209090, 2021). "For CSS, patients with cancer-specific death presented higher expression patterns of RGPD8, BAIAP2L1, and DDX11 and lower expression patterns of SLC16A9, FRAS1, AQP1, TMEM38B, and PRUNE2, in both the univariate and multivariate analyses." (PMID 31963294, 2020). "Among differentially methylated genes, DSCAML1 exhibited higher expression in Cluster II tumors (not statistically significant), whereas BAIAP2L1 showed significantly lower expression in malignant tumors, consistent with locus-specific hypermethylation discussed previously." (PMID 41597272, 2026). "In addition to actin-related functions of BAIAP2L1, which are mainly elucidated from bacterial studies, the discovery of BAIAP2L1 in the IR-IRS-AKT pathways may shed light to its role in cancer-specific metabolism." (PMID 26222696, 2015).
peripheral nerve disorders (1 paper, 2023). "For example, rs11385557 in the intronic region of BAIAP2L1 was found in OpenGWAS database to be significantly (P < 7.69 × 10–5) associated with peripheral nerve disorders (#8) which is consistent with RA patients often experiencing peripheral neuropathy with pain, numbness, and muscle weakness." (PMID 36750873, 2023).
BAIAP2L1 also shares sentences with these, for which no sentence is quoted: bladder cancer (3 papers); infection (3); Insulin resistance (2); type 2 diabetes (2); benign tumors (1); breast carcinoma (1); cervical cancer (1); gastric cancer (1); Glucose intolerance (1); hyperglycaemia (1); hypogonadism (1); liver cancer (1); lung adenocarcinoma (1); neuroblastoma (1); papillary thyroid cancers (1); prostate carcinoma (1); thyroiditis (1); virus infection (1).